FOXP3 (forkhead box P3)
Diseases named in the same sentence as FOXP3 in open-access papers (continued):
Sharing a sentence is not in itself a finding about the gene and the disease.
HIV-1 infection (21 papers, 2007 to 2026). The type species of lentivirus and the etiologic agent of acquired immunodeficiency syndrome (AIDS). "Our data suggest that a higher degree of exhausted CD4+ T cells during HIV-1 infection is partly linked to higher frequency of CD25+ FoxP3+ CD4+ T cells." (PMID 29403500, 2018). "HIV-1 infection results in downregulation of Foxp3 expression in Treg cells followed by loss of suppressive activity and alterations in cytokine expression profile." (PMID 29710792, 2018). "Moreover, I-TAC is a CXCR3-ligand that when elevated in the plasma has been shown to promote CD4 T-cell (FoxP3+) activation that was also associated with severe disease progression in HIV-1 infection." (PMID 37874153, 2023). "In this study, the perturbations of Foxp3+Helios+ Treg cells were characterized, and the association between monocyte subsets and their PD-1 expression and Foxp3+Helios+ Treg cells was evaluated during acute HIV-1 infection." (PMID 31651258, 2019). "In this study, the perturbations of Foxp3+Helios+ Treg cells were characterized, and the association between monocyte subsets and their PD-1 expression and Foxp3+Helios+ Treg cells was evaluated during HIV-1 infection." (PMID 31651258, 2019). "On the contrary, a closer examination of all PD-1+IFN-γ+CD4+ cells (Th1 like cells) revealed that HIV-1 infection and exogenous spermidine induced FOXP3 expression in them." (PMID 36693889, 2023). "During acute HIV-1 infection, the frequency of Foxp3+Helios+CD45RA+ Treg cells was inversely correlated with the frequency of intermediate CD14++CD16+ monocytes, whereas it was positively correlated with the PD-1 density on intermediate CD14++CD16+ monocytes." (PMID 31651258, 2019). "The frequency of Foxp3+Helios+CD45RA+ Treg cells is significantly higher in patients with acute HIV-1 infection than those of healthy controls and chronic HIV-1-infected patients undergoing combined antiretroviral therapy." (PMID 31651258, 2019). "In the present study, we characterized the perturbations of Foxp3+Helios+ Treg cells during HIV-1 infection." (PMID 31651258, 2019). "Some studies support the notion that FoxP3 inhibits HIV-1 infection by interfering with HIV-1’s LTR transcription activation while others demonstrate enhanced HIV-1 production in FoxP3 positive cells." (PMID 31487324, 2019). "Summing up, the 2G-S24P and 2G-S16 anionic dendrimers protected the Treg cells from the Foxp3 downregulation induced by the HIV-1 infection." (PMID 26785250, 2016). "These dendrimers were highly active against HIV-1 preventing the infection of Treg, and were able to protect the Treg from the Foxp3 downregulation induced by the HIV-1 infection." (PMID 26785250, 2016). "One of the main effects of HIV-1 infection on the Treg cells is the downregulation of the Foxp3 expression, which is crucial for the functionality of the cells." (PMID 26785250, 2016). "There was a significant decrease in the frequency of Tregs in the early phase of the HIV-1 infection correlating with significant decrease in Foxp3 expression." (PMID 25198707, 2014). "A significantly higher T-regulatory cell (Treg) frequency coupled with the high FoxP3 expression in the CD4 T-cells indicated an immunosuppressive environment in the advance stage of HIV-1 infection." (PMID 25198707, 2014). "Investigations of T cells with regulatory properties in HIV-1 infection have so far been mostly limited to classical, CD25hi and/or FoxP3 expressing Treg." (PMID 23382678, 2013). "Naturally occuring Treg (nTreg) (CD4+CD25+Foxp3+) exist in all individuals and play a critical role in chronic HIV-1 infection." (PMID 20455275, 2010). "HIV-1 infection enhanced Foxp3 expression in activated CD4+CD25- T cells; which was also abrogated by blockade of endogenous TGF-β." (PMID 17688698, 2007). "However, certain types of cells, such as macrophages and CD4+Foxp3+ regulatory T cells (Tregs), have been shown to resist HIV-1 infection despite co-expressing CD4 and co-receptors." (PMID 42088414, 2026).
HIV-1 infection (continued). "ODC-1 blocking and GC7 inhibited the FOXP3 induction during HIV-1 infection." (PMID 36693889, 2023). "During acute HIV-1 infection, the frequency of Foxp3+Helios+CD45RA+ Treg cells is inversely correlated with the frequency of the intermediate CD14++CD16+ monocyte subset, but positively correlated with PD-1 expression in both intermediate CD14++CD16+ and non-classical CD14+CD16++ monocyte subsets." (PMID 31651258, 2019). "In addition, the PD-1 density on non-classical CD14+CD16++ monocytes is positively correlated with the frequency of Foxp3+Helios+CD45RA+ Treg cells during acute HIV-1 infection." (PMID 31651258, 2019). "Understanding the effects of monocyte subsets and their PD-1 expression on Foxp3+Helios+ Treg cells may be helpful for developing different therapeutic strategies to manipulate immune responses against HIV-1 infection." (PMID 31651258, 2019). "Besides, a X4-HIV-1NL4.3 strain was used to infect the Treg cells because this strain has previously demonstrated a high HIV-1 infection and replication in Treg cells, and a high effect on the Foxp3 expression." (PMID 26785250, 2016). "Moreover, the treatment with anionic dendrimers has demonstrated to be effective in inhibiting the HIV-1 infection of Treg cells, and diminishing the effects on Foxp3 expression produced by the HIV-1 infection." (PMID 26785250, 2016). "To further explore the cytokine profiles during HIV-1 infection, we measured the expression of the transcription factors reported to be associated with different T-cell lineages, i.e. T-bet, GATA-3, Foxp3 and ROR-γt that are expressed by Th1, Th2, Treg and Th17 respectively." (PMID 22276176, 2012). "Based on this feature, several probiotics and the PSA of B. fragilis have been used to inhibit the progression of inflammation through the upregulation of Foxp3+ Tregs and to promote the immunotherapy of IBD or the HIV-1 infection." (PMID 33643302, 2020). "The frequency of Foxp3+Helios+CD45RA+ Treg cells was inversely correlated with CD4 T-cell counts and CD4/CD8 ratio during acute and chronic HIV-1 infection." (PMID 31651258, 2019). "Foxp3+Helios+CD45RO+ Treg cells and Foxp3+CD25+CD45RO+ Treg cells were depleted relative to HCs in patients with HIV-1 infection and/or syphilis." (PMID 31024549, 2019). "Until now, the effects of monocyte subsets and their PD-1 expression on Foxp3+Helios+ Treg cells have not been fully characterized, especially during acute HIV-1 infection." (PMID 31651258, 2019). "Studies performed with either whole PBMCs or sorted aTregs and FOXP3+ non-Tregs cells showed that these two populations of FOXP3+ T cells were highly permissive to HIV-1 infection." (PMID 23285102, 2012). "Results showed that Tregs were positive for surface CD4 (i.e., CD4− FOXP3+ cells were absent), indicating that the disappearance of Tregs during the acute phase of infection was not due to surface CD4 down-regulation, but rather to depletion by HIV-1 infection." (PMID 24339781, 2013).
metastatic tumor (21 papers, 2009 to 2026). "FOXP3+ T cells have been shown to be increased in numbers in SLNs, in particular in metastatic nodes; even micro-metastatic disease was associated with increased levels of FOXP3+ T cells." (PMID 29390966, 2018). "Furthermore, according to an evaluation using immunohistochemistry, the density of TIL subsets, such as CD4+, CD8+ and FOXP3+ TILs, in the primary tumor was significantly associated with that in the metastatic tumor." (PMID 29614981, 2018). "Furthermore, the number of CD4+, CD8+ and FOXP3+ TILs in the primary tumor was also significantly associated with these numbers in the metastatic tumor (r = 0.634, p = 0.001; r = 0.700, p < 0.001; r = 0.559, p = 0.006, respectively)." (PMID 29614981, 2018). "Furthermore, we found that metastatic tumors with higher surface PD-L1 expression were associated with a CD4-high/Foxp3-high TIL subpopulation (p = 0.015), which would denote an unfavorable immune microenvironment in untreated patients." (PMID 26317902, 2015). "CD8+ T cells were significantly less frequent in metastatic tumors, whereas both CD4+ and CD8+ T cells present in primary tumors expressed more transcription factors associated with suppressive properties, including FoxP3 and RORγt." (PMID 41418102, 2026). "Although the median value of each of the TIL subsets was higher in the primary tumor than in the metastatic tumor, significant differences were observed in only FOXP3." (PMID 29614981, 2018). "This discordance can likely be attributed to the CD4+ helper T-cell content, as the remaining two subsets examined, CD8+ cytotoxic T-cells and Foxp3+ TILs, were concordant between primary and metastatic disease." (PMID 26317902, 2015). "The Foxp3+/IDO+ group consisted almost exclusively of SLN with metastatic disease, whereas the Foxp3-/IDO- group contained almost all of the control SLN (p = 0.007)." (PMID 19604349, 2009). "As CD8+FoxP3+CD25+ T cells in CxCa metastatic tumors were previously reported to be immune suppressive and as expression of multiple immune checkpoints is generally regarded as a sign of exhaustion, we assessed the functional status of this subset after polyclonal stimulation." (PMID 30755279, 2019). "In addition, according to the immunohistochemistry evaluation, the density of CD4+, CD8+ and FOXP3+ TILs in the primary tumor and that in the metastatic tumor were significantly correlated with that in the metastatic tumor." (PMID 29614981, 2018). "Immune subset analyses revealed that the combination therapy not only enhanced CD4+Foxp3- T-cell expansion at the metastatic tumor site (lung) and in the periphery (spleen and DLN), but also augmented memory formation compared to the untreated and monotherapy controls." (PMID 29207606, 2017). "ENTPD1 expressed on CD4+Foxp3+ regulatory T cells (Tregs), and in mice, it could inhibit natural killer (NK) cells and promote hepatic metastatic tumor growth, whereas inhibition of the enzymatic activity of ENTPD1 could be used as an adjunct therapy for hepatic malignancies." (PMID 36998605, 2023). "Expressed in most primary and metastatic tumors with reduced immune infiltration.Strong correlation with the density of CD3+, CD8+T cells and FOXP3+regulatory T cells." (PMID 38605944, 2024). "When comparing primary to metastatic tumors, ID8-WT metastatic tumors had a higher abundance of FOXP3+ cells." (PMID 36311166, 2022). "In our study, high levels of FOXP3+ and CTLA-4+ T cells were documented in metastatic tumours in the ALNs and were higher than the levels in the corresponding primary tumours." (PMID 29390966, 2018). "Paraffin sections from patients with (n = 9) or without (n = 9) progressive endometrial cancer (recurrent or metastatic disease) were assessed for the presence of CD4+ (helper), CD8+ (cytotoxic) and Foxp3+ (regulatory) T-lymphocytes and PR expression." (PMID 22295114, 2012).
metastatic tumor (continued). "Lastly, by immunohistochemistry, CD3+ FOXP3+ cells and by RNA-Seq, FOXP3 expression is not significantly changed between the primary and recurrent/metastatic tumor." (PMID 33796222, 2021). "Foxp3, a marker of Tregs, was substantially decreased, and CD8 (+), a marker of cytotoxic T lymphocytes, was substantially increased in anti-TGF-β antibody-treated groups in metastatic tumor lesions." (PMID 22415727, 2012). "Furthermore, high PD-L1-expressing metastatic tumors, but not the corresponding primary lesions, were associated with TILs that contained high densities of both CD4+ and Foxp3+ T-cells." (PMID 26317902, 2015). "While there was no evident change in T cell density during progression to metastatic disease, we did observe a decrease in CD3+, CD8+ and FoxP3+ T cells during chemotherapy, both in the neoadjuvant and palliative setting." (PMID 35046958, 2021).
parasitemia (21 papers, 2010 to 2022). "Depletion of Tregs using a Foxp3-diptheria toxin receptor (DTR) system during this temporal window lead to dramatically accelerated control of parasitemia." (PMID 32043415, 2020). "Recent data suggest that in certain chronic parasite infections, induction of Foxp3+ Tregs is important in suppression of protective immunity and development of chronic infection." (PMID 24098124, 2013). "In this study, a significant increase of circulating CD4+CD25+FOXP3+cells producing the IL-17 was observed in infected donors, corroborating previous studies on other parasitic diseases." (PMID 22087344, 2011). "Altered Foxp3 expression could also be detected in the context of parasitic infections: During chronic infection with Leishmania of the Viannia subgenus, a decreased Foxp3 expression was detected." (PMID 34691057, 2021). "Previously, we observed that CD4+Foxp3+ Tregs increase significantly in the spleen of infected B6 mice during acute P. chabaudi AS infection followed by a significant increase in effector CD4+T-bet+IFN-γ+ Th1 cells around the time of peak parasitemia." (PMID 30915078, 2019). "Moreover, the gut microenvironment or parasitic infection favours the reprogramming of Foxp3+ TREG cells into effector T cells and promotes host immunity." (PMID 22545118, 2012). "Foxp3+ Tregs influence immunity to viral, bacterial or parasitic infections." (PMID 22928057, 2012). "Thymic or peripheral Foxp3+ nTREG cells manifest prominent functional plasticity and readily reprogram into Th1 and Th17 effector cells, particularly in the gut microenvironment or sites of parasitic infection." (PMID 22545118, 2012). "Immunohistochemistry for eight antibodies (CK19, CD3, Foxp3, CD20, Iba1, CD68, CD163, and CD204) was conducted to analyze the pathology of these parasitic infections." (PMID 32714946, 2020). "Consistent with this theory, neutralization of Tregs by Foxp3-depletion led to increased quantities of activated CD4 T cells and rapid control of parasitemia." (PMID 32043415, 2020). "Conversely, we also observed an increased number of circulating CD4+CD25+FoxP3+ T cells that produce IFN-γ and IL-17 in peripheral blood of P. vivax-infected donors, which also correlated with the levels of parasitemia." (PMID 20224778, 2010). "Our results show a significant increase of circulating CD4+CD25+FoxP3+GITR+ and CD4+CD25+FoxP3+CTLA-4+ lymphocytes in P. vivax-infected donors, which was further correlated with level of parasitemia observed in the same individuals." (PMID 20224778, 2010). "The frequency of CD4+ICOS+FoxP3+ Tregs was significantly higher in lethal parasitic infection as compared to the non-lethal parasite." (PMID 35109868, 2022). "In this setting we could not identify a higher proportion of FoxP3+ Treg cells in individuals developing parasitemia in comparison to those not developing parasitemia." (PMID 33815377, 2021). "These CD8+Foxp3+ T cells have not yet been described functionally in parasitic diseases, but could represent cells with suppressive ability." (PMID 24205367, 2013). "FoxP3+ regulatory T cells (Tregs) produce TGF-beta and IL-10 but their role in this parasitic disease is still not clear." (PMID 32517744, 2020).
Splenomegaly (20 papers, 2008 to 2025). Abnormal increased size of the spleen. "We therefore developed a clinical scoring system for Foxp3 deficiency, using a 0–3 scoring system covering splenomegaly, weight-change, behavior changes (in particular, hunching), and separate measures of dermal thickening and redness on the skin, tail, ears and around the eyes." (PMID 37156988, 2023). "Furthermore, Foxp3-Cre Pak2-deficient mice presented with splenomegaly, lymphadenopathy and severe thymic atrophy, suggestive of ongoing inflammation." (PMID 29213081, 2017). "While the continuous Treg depletion led to flagrant splenomegaly and lymphadenopathy, these manifestations were unexpectedly mild following continuous Foxp3 degradation in Foxp3AIDR26TIR1(F74G) mice treated with 5-ph-IAA for the same duration (Figure." (PMID 40470210, 2025). "While continuous Treg cell depletion led to flagrant splenomegaly and lymphadenopathy, these manifestations were unexpectedly mild following continuous Foxp3 degradation in Foxp3AIDR26TIR1(F74G) mice treated with 5-ph-IAA for the same duration." (PMID 41062655, 2025). "Foxp3YFP-CrePik3c3flox mice also developed splenomegaly and lymphadenopathy, suggesting an ongoing autoimmune lymphoproliferative disease, similar to what has previously been observed in Foxp3 knockout and Scurfy mice." (PMID 39664390, 2024). "The adoptive transfer of CD4+Foxp3+ or CD4+Lrig1+ T cells markedly alleviated the IBD symptoms such as body weight loss, inflammation in the colon, splenomegaly, and histological score, while these IBD symptoms were observed in CD4+Lrig1− T cell recipients." (PMID 37666819, 2023). "As expected, both Treg and CD4+Foxp3– T cells from the Tet2/3fl/flFoxp3Cre mouse with less severe splenomegaly more closely resembled the corresponding WT cells, whereas cells from the mouse with more severe splenomegaly were less similar to WT." (PMID 31043609, 2019). "Deletion of Foxp3+ Treg induced severe pathology including wasting disease, splenomegaly and lymphadenopathy." (PMID 22849659, 2012). "We found that blood levels of FOXP3+ Tregs (-2.5 ± 0.56, p<0.001) and eTregs (-1.3±0.6, p = 0.03) were lower in patients with severe liver (HF++ or HF+++) and spleen (SplM) disease who had undergone splenectomy than in HF+++ subjects with splenomegaly." (PMID 26731721, 2016). "Interestingly, Foxp3−/− mice develop a splenomegaly that is accompanied by splenic cfu-GM increase, and this was inhibited by the infusion of CD25+ Treg cells at birth." (PMID 23200826, 2012). "Transfer of NRP1+PD‐1+ Foxp3− Th cell elicited disease progression in protected male BXSB.Yaa Nr4a2 cKO mice, with splenomegaly and increases in serum antibodies, including ANA." (PMID 36069030, 2022). "Tet2/3fl/flFoxp3Cre mice develop an inflammatory disease with splenomegaly and leukocyte infiltration into lung, and CD4+Foxp3+ Treg cells, CD4+Foxp3− and CD8+ T cells in these mice display an activated phenotype." (PMID 31043609, 2019). "Due to stochastic activity of the Foxp3 promoter, constitutive overexpression of STAT5B-CA led to progressive splenomegaly and hematopoietic neoplasia in Foxp3YFP-Cre/YRosa26Stat5b-CA/wt mice (data not shown), similar to that after STAT5 activation in other hematopoietic compartments." (PMID 35874700, 2022). "In terms of absolute numbers, we have found that Stat1−/− mice have essentially normal numbers of Foxp3+ cells, but these mice have profound splenomegaly and approximately ten times more CD4+ T cells with an activated phenotype (CD25+ Foxp3−) than wild-type controls (not shown)." (PMID 18792404, 2008).